CEP95 (centrosomal protein 95)
Synonyms: CCDC45; DKFZp667E1824
Tractability: PROTAC: ubiquitination databases record sites on it.
Gene: Protein-coding gene on chromosome 17 (64,506,767 to 64,542,461, forward strand). Ensembl gene ENSG00000258890.
Subcellular location: Cytoplasm, cytoskeleton, microtubule organizing center, centrosome; Cytoplasm, cytoskeleton, spindle pole
Subcellular location (Human Protein Atlas): Centriolar satellite; Cytosol
Gene Ontology:
Molecular function: protein binding
Cellular component: centrosome; spindle pole
Genetic constraint (gnomAD): Loss-of-function variants: 64 observed, 74.25 expected, observed/expected ratio (o/e) 0.86, 90% interval 0.7 to 1.06. The upper end of that interval is the gene's LOEUF score, 1.06, which puts it in group 4 of 6, group 1 being the genes least tolerant of losing a copy. Missense variants: 697 observed, 672.12 expected, observed/expected ratio (o/e) 1.04, 90% interval 0.97 to 1.1. Synonymous variants: 224 observed, 241.98 expected, observed/expected ratio (o/e) 0.93, 90% interval 0.83 to 1.03.
Homologues: Orthologues: chimpanzee CEP95 (99% identical), macaque CEP95 (95% identical), dog CEP95 (82% identical), rabbit CEP95 (82% identical), pig CEP95 (82% identical), guinea pig CEP95 (80% identical), mouse Cep95 (73% identical), rat Cep95 (72% identical), tropical clawed frog cep95 (43% identical).
Diseases named in the same sentence as CEP95 in open-access papers:
CEP95 is named in the same sentence as 4 diseases in open-access papers, as found by Europe PMC text mining. Sharing a sentence is not in itself a finding about the gene and the disease.
CEP95 shares sentences with these, for which no sentence is quoted: cancer (1 paper); cataract (1); hepatocellular carcinoma (1); tumor (1).